CCL3 (C-C motif chemokine ligand 3)
Diseases named in the same sentence as CCL3 in open-access papers (continued):
Sharing a sentence is not in itself a finding about the gene and the disease.
cancer (172 papers, 2007 to 2026). A tumor composed of atypical neoplastic, often pleomorphic cells that invade other tissues. "Conversely, CCL3 supports metastasis by recruiting cancer-associated fibroblasts (CAFs) via CCR5, leading to bone metastasis." (PMID 40236693, 2025). "Transcriptomic analyses revealed that pancreatic stromal cells co-cultured with PAK1-modulated cancer cells exhibited elevated CCL3 expression, which was linked to activation of interferon pathways and myofibroblast differentiation." (PMID 41153795, 2025). "CCL3 was included as it is secreted by many types of PBMCs and has been implicated in cancer and other diseases." (PMID 37780865, 2023). "Lower levels of CCL3 [also known as macrophage inflammatory protein 1α (MIP-1α)] have been associated with a poor prognosis and increased risk of some types of cancers." (PMID 35385679, 2022). "Obviously, it is more the potency of CCL3 to trigger the colonic accumulation of cancer-associated fibroblast and the subsequent production of fibroblast-derived growth factors that underlies its pro-tumorigenic character." (PMID 36428508, 2022). "In bones, on the other hand, there is an increase in the expression of CCL3 in bone-marrow-derived monocytes caused by the secretion of epidermal growth factor (EGF) by cancer cells." (PMID 33076281, 2020). "Multiple DEGs, including FEN1, BCAT1, AGPS and CCL3, have been implicated in the progression of various cancers." (PMID 29033691, 2017). "CCL3 has also been implicated in the regulation of cancer cell growth, angiogenesis and metastasis of different tumors such as melanoma, colorectal cancer, and renal cell carcinoma." (PMID 24047437, 2013). "CCL3 causes migration and invasion of cancer cells via CCR5." (PMID 33076281, 2020). "Moreover, CCL3 has been implicated in regulation of cancer cell growth and metastasis of different tumors." (PMID 25132730, 2014). "This is supported by previous investigations demonstrating CCL3’s multifaceted role in various cancers, particularly regarding its regulation of the immune microenvironment in AML." (PMID 41208992, 2025). "In the present study, we found that TNF, IFN, IRF1 and IRF5, IL-6, IL-1β, and CCL3 were upregulated in EBV-positive SCC25 cancer cells compared to EBV-negative SCC25 cancer cells." (PMID 39941858, 2025). "Regarding the key interaction between T cells and cancer cells, increased expression of ligand-receptor pairs MIF_TNFRSF10D, CD55_ADGRE5, CD226_NECTIN2, CCL3L1_CCR1, and CCL3_CCR1 was observed." (PMID 39986271, 2025). "Six key recent studies demonstrate how elevated CCL3 drives cancer cell proliferation, invasion, and metastatic potential." (PMID 41153795, 2025). "Consistent with this phenotype, PT-associated macrophages expressed inflammatory cytokines (TNF, IL6) and pro-tumorigenic factors (CCL2, CCL3, CCL4, CXCL16) linked to cancer progression and invasiveness." (PMID 41346635, 2025). "CCL3 and its connection to cancer and CIPN is a fascinating target for future cancer neuroscience studies." (PMID 41153795, 2025). "In this review, we evaluate current evidence to explore the dual role of CCL3 at the interface of cancer progression and chemotherapy-induced neuronal damage." (PMID 41153795, 2025). "Functionally, CCL3 promotes cancer growth by stimulating proliferation, migration, and invasion, acting via the TRAF6/NF-κB pathway." (PMID 38338661, 2024). "The chemokine acts similarly to CCL3 with respect to being a promoter of cancer cell proliferation and survival and a facilitator of metastasis." (PMID 38338661, 2024). "This phenomenon suggests that CCL3 affects colorectal cancer’s progression and metastasis through cancer cell motility." (PMID 39334887, 2024).
cancer (continued). "Compared with normal tissues, CCL3 was highly expressed in cancer tissues, while CCR5, NF-κB, TRAF6, and PI3K were highly expressed in cancer tissues and metastatic lymph nodes." (PMID 35935327, 2022). "Chemokine C-C motif chemokine ligand 3 (CCL3) plays an important role in the invasion and metastasis of malignant tumors." (PMID 35935327, 2022). "The experimental results confirmed that CCL3 can promote the proliferation of cancer cells, and its expression is closely related to TRAF6/NF-κBmolecular pathway." (PMID 35935327, 2022). "Recent studies have found that CCL3 plays a role in the invasion and metastasis of malignant tumors." (PMID 35935327, 2022). "CCL3 has been reported to play a role in the proliferation, migration, and invasion of malignant tumor cells." (PMID 33981848, 2021). "Statins disrupt communication between cancer cells and mesenchymal stromal cells (MSC) by inhibiting CCL3 secreted by cancer cells and IL-6 and CCL2 produced by MSC." (PMID 34858839, 2021). "In primary squamous lung cancer, statins break the communication between cancer cells and mesenchymal stromal cells (MSCs) by inhibiting CCL3 secreted by cancer cells and IL-6 and CCL2 produced by MSCs." (PMID 32843638, 2020). "In NK cells, chronic hypoxia reduces the expression of CCL3/MIP-1α and other pro-inflammatory cytokines, which contributes to cancer immunoevasion." (PMID 32781743, 2020). "The cancer cell recruits macrophages through the CCL2→CCR2 axis; these macrophages then secrete CCL3, which causes the retention of these cells in the metastatic niche in an autocrine manner via CCR1." (PMID 33076281, 2020). "The present study is the first report which revealed that the expression of both CCL3 and CCR5 in human cancer tissue is associated with poor patient prognosis." (PMID 32457351, 2020). "CCL3 and CCL4 cause increased expression of VEGF in a cancer cell, a growth factor causing angiogenesis." (PMID 33076281, 2020). "Chromatin immunoprecipitation (ChIP) assay showed that PARP2 bound to CCL3 proximal promoter in both IMCs and cancer cells." (PMID 32221289, 2020). "CCL2 and CCL3 are secreted by M1 macrophages which promoted a strong immune response to kill the cancer cells." (PMID 32256661, 2020). "There are a few reports which have found that high levels of CCL3 and/or CCR5 expressions in human cancer tissue were associated with poor prognosis." (PMID 32457351, 2020). "Our results indicate that cancer cell lines significantly upregulated genes associated with M1 monocytes including PDL1, TNF-α, IL-1β, IL-6, IL-8, CCL3, and prostaglandin-endoperoxidase synthase 2 (PTGS2)." (PMID 29668679, 2018). "In our study, expression of proinflammatory chemokines IL-8, CXCL1, CXCL2, and CCL3 was upregulated in the early stages of cancer progression." (PMID 27143385, 2016). "We found that siRNA against both AMPKα1 and AMPKα2 reduce CCL3-mediated cancer migration, implying that AMPKα1 and AMPKα2 are involved in CCL3-induced migration activity." (PMID 24047437, 2013). "Specifically, we evaluate whether CCL3 may serve as a molecular link between cancer progression and the development of neuropathic pain." (PMID 41153795, 2025). "Therefore, it is hard to draw conclusions regarding the relationship between CCL3 levels and cancer progression or staging based on this data." (PMID 41153795, 2025). "CCL3 is a monokine with chemokinetic and inflammatorycharacteristics that binds to the CCR4 and CCR5 receptors; it is oneof the main substances produced by CD8+ T cells that suppress virusesthat drive mutation in cancer." (PMID 40047620, 2025). "Furthermore, CCL3 has been reported to induce angiogenesis and facilitate osteolytic bone metastases of several cancers." (PMID 38338661, 2024). "Accordingly, CCL3 activities that hamper cancer growth have been also demonstrated." (PMID 38338661, 2024).
cancer (continued). "In additional experiments, where we compared healthy mice to 4PYR-treated animals, we found that 4PYR has contributed to significantly increased expression of cytokines related to inflammation and cancer progression, such as CCL3, CXCL1, CCL5 or IL-1A and IL-1B." (PMID 39795893, 2024). "CCL3 on CD8+ T cells was also predicted to interact with CCR1 or CCR5 on myeloid cells and CXCL13 on CD8+ T cells was predicted to interact with CXCR5 on B cells or ACKR4 on cancer-associated fibroblasts." (PMID 39478117, 2024). "CCL3 may contribute to cancer progression by stimulating leukocyte accumulation, angiogenesis, and tumorigenesis." (PMID 38274108, 2023). "Interestingly, a recent study of liver tumor also described that the co-enrichment of CCL3+ neutrophils and SPP1+ macrophages was associated with poor prognosis, indicating a similar mechanism across different cancer types." (PMID 36869384, 2023). "Both CCL3 and IL-1β are known to participate in cancer pathogenesis." (PMID 38273861, 2023). "While downregulated in the ID subgroup, B, M, and lesser T cell subgroups showed upregulated signaling of several chemokines (CXCL9/10/11, CCL3/13/18) to their cognate receptors on T and myeloid cell subsets, suggesting that cancer-cell-secreted chemokine gradients contribute to immune infiltration." (PMID 36368318, 2022). "Indeed, CBD-treated cancer cells exhibited a reduction in secreted granulocyte macrophage colony-stimulation factor (GM-CSF) and C-C motif chemokine ligand 3 (CCL3) cytokines, which are important for macrophage recruitment and activation." (PMID 34943903, 2021). "Similarly, the undifferentiated MPRO cells expressed higher levels of Il-1β, Ccl2, Ccl3, Ccl4, and iNos when cultured in the supernatant of cancer cells compared to SF media." (PMID 33049964, 2020). "The immune response reduces the expression of CCL3 in cancer cells via the activation of β-catenin." (PMID 33076281, 2020). "Platelets also secrete many factors, including CCL3, which support the cancer cell." (PMID 33076281, 2020). "Previous study suggest that CCL3 is overexpressed in many cancer types." (PMID 24047437, 2013). "In contrast, the secreted CCL3/CCL4 could serve as a biomarker of tumors containing a G4 cancer cell type." (PMID 20021671, 2009). "CCL3 (Macrophage Inflammatory Protein-1 alpha, MIP-1α) belongs to the C-C chemokine family and is involved in the occurrence and development of various malignant tumors." (PMID 40723784, 2025). "We also discovered that M2 releases a protein called MIP-1α (CCL3), which enhances the ability of cancer cells to spread." (PMID 40940877, 2025). "For instance, in response to cancer cell conditioned media, CAFs upregulate expression of chemokines such as CCL2, which, together with CCL3 and CCL4 can recruit myeloid cells to the TME." (PMID 39743376, 2025). "For instance, researchers have utilized a 12-gene expression signature (including CCL2, CCL3, CCL4, CCL5, and others) to assess TLS presence across different cancer types." (PMID 39620224, 2024). "CCL3 and CCL4 can also be produced by MDSC and TAMs themselves, leading to both autocrine and paracrine STAT3 activation and subsequent enhancement of cancer cell proliferation, invasion, and epithelial–mesenchymal transition." (PMID 38108458, 2024). "TNF-α induced a significant increase in the secretion of chemokines and cytokines from CT26 cancer cells including CCL2, CCL3, CCL4, CCL5 and G-CSF." (PMID 39310770, 2024). "CCR5 binds with high- affinity to CCL5, CCL3 (MIP-1a), and CCL4 (MIP-1b) in cancer cell membranes to mediate diverse signaling cascades in response to its ligands." (PMID 37553567, 2023). "PDCD1, TGFB1, CXCL8, CCL3, CCL4, and CCL5 were highly expressed in subTME-IS; CXCL2 and CXCL12 were highly expressed in subTME-ICI, which was consistent among cancer types." (PMID 38002057, 2023).
cancer (continued). "There are 28 types of chemokines (CCL1-CCL28) belonging to the CC chemokine subfamily, among which CCL2, CCL3, CCL5, CCL15, CCL18 and CCL26 exert some regulatory effects on pathological processes such as TAMs infiltration and polarization in cancer." (PMID 36173487, 2023). "In this way, CCL3 (also known as macrophage inflammatory protein-1α, i.e., MIP-1α) and CCL4 (MIP-1β) are pro-inflammatory chemokines that display both pro-and anti-cancer properties." (PMID 35406791, 2022). "Numerous IDE substrates are highly relevant in the context of cancer, in particular IGF-II, insulin and CCL3." (PMID 35406791, 2022). "Mechanistically, β‐catenin upregulates cancer cell surface metadherin, which communicates through CEACAM1 expressed on macrophages to produce CCL3." (PMID 35403834, 2022). "To this aim, we measured CCL2, CCL3, CCL4, and CCL5 by CBA in TCM from different cancer types or in cultures of BM cells stimulated with the same TCMs or with recombinant cytokines involved in MDSC differentiation." (PMID 35064009, 2022). "Since CXCL9 and CCL3 are IFN-γ-related chemokines, here we focused on studying the anti-cancer effects of IFN-γ and TNF-α." (PMID 33175182, 2021). "Given the importance of CCL3 and CCR5 in cancer progression, we tested the impression of BFT-1 on the expression of CCR-5/CCL3, TRAF6/NF-κB." (PMID 33981848, 2021). "CCR5 is a receptor of CCL3, and CCL3/CCR5 axis was found to play important roles in the invasion and metastasis of malignant tumors." (PMID 33981848, 2021). "The increase in the number of immune cells, induced by CCL3 and CCL4, makes these chemokines a potentially important element of cancer immunotherapy." (PMID 33076281, 2020). "We observed higher levels of Il-1β, Ccl2, Ccl3, Il23, and iNos mRNA in the differentiated MPRO cells cultured in the supernatant of cancer cells compared with MPRO cells cultured in SF media." (PMID 33049964, 2020). "Recent findings demonstrate that one NK cell population possesses potent cytolytic activity against targeted cancer cells, while others uniquely secrete various inflammatory cytokines (IFN-γ, TNF-α, and GM-CSF) and chemokines (CCL3 and CCL5)." (PMID 32231116, 2020). "While Ponader and co-workers have reported that ibrutinib decreases secretion of CCL3 and CCL4 in CLL cells, the cancer cell-autonomous survival function of these chemokines is yet to be explored." (PMID 28036258, 2017). "We observed that the AMPK inhibitors, namely, Ara A and compound C, antagonize CCL3-mediated cancer migration and MMP-2 expression, suggesting that AMPK activation is an obligatory event in CCL3-induced migration activity in these cells." (PMID 24047437, 2013). "We found up-regulation of the highly potent macrophage attracting factors: CCL2 (MCP-1), CCL3 (MIP-1α), CCL4 (MIP-1β) and CCL5 (RANTES) as well as CCR5 in cancer cells grown as co-culture with macrophages." (PMID 22353646, 2012). "The real-time qPCR confirmed the CCL2, CCL3, CD163, CSF1R, MMP9, HIF1, VEGF-C up-regulation in cancer cells grown as a co-culture with macrophages." (PMID 22353646, 2012). "Additionally, the relationship exhibited by CCL3/5 and CCR1 was found to correspond with pro-inflammatory macrophage polarisation, which in turn facilitates the phagocytosis of cancer cells." (PMID 39901202, 2025). "CCL3 is a chemokine involved in various inflammatory responses through chemokine receptors (namely CCR1 and CCR5), and has a key role in several human diseases such as cancer and HIV infection." (PMID 36814903, 2023). "Besides, a variety of cancers have heightened levels of neutrophil-specific chemokines such as CXCL6, CXCL8 (IL-8), and CCL3 (MIP-1α)." (PMID 37158964, 2023). "Elevated levels of pADPr have also been associated with the release of various chemokines, including monocyte chemoattractant protein-1 (MCP-1 or CCL2), eotaxin (CCL11), macrophage inflammatory proteins MIP-1α (CCL3) and MIP-1β (CCL4), all of which are known to promote cancer invasion." (PMID 35585513, 2022).
cancer (continued). "To further identify the potential soluble factors from MPE-Mφ-derived M1 macrophages might inhibit cancer cell growth, we performed experiments to examine the effects of M1-related cytokines (TNF-α, CXCL9, IFN-γ, or CCL3) on A549 cell proliferation." (PMID 33175182, 2021). "In addition, Statins restrict tumor cell growth by inhibiting CCL3 secreted by cancer cells and IL-6 and CCL2 produced by MSC, thereby disrupting the communication between cancer cells and MSC." (PMID 34858839, 2021). "In patients with polyps, ACKR2 markedly correlated solely with CCL3, which was also the strongest correlation in CRC patients, although in cancer the significant correlations were present between the receptor and all examined chemokines from MIP and MCP family." (PMID 33374792, 2020). "Double IF of CCL3 and CD204 confirmed that CCL3 was expressed both by TAMs and cancer cells." (PMID 32457351, 2020). "On the other hand, CCL3 and CCL4 also have pro-cancer effects." (PMID 33076281, 2020). "ChIP assay showed that β-catenin binding at CCL3 promoter was significantly augmented by the KD of PARP2 but not by PARP1 in cancer cells." (PMID 32221289, 2020). "The role of CCL3 and its receptor CCR1 in bone metastasis have been best characterized in the context of MM and blockade of this receptor has promising effects in pre-clinical animal cancer models." (PMID 29930538, 2018). "The recruited MAMs secreted CCL3, which could promote MAM-cancer cell interactions and enhance subsequent seeding of cancer cells into lungs." (PMID 30597969, 2018). "We found that overexpression of EBNA2 and its targets, CCL3 and CCL4, led to doxorubicin resistance, independent of the pathway underlying LMP1-mediated protection of cancer cells against chemotherapeutic agents." (PMID 28036258, 2017). "Our gene expression analysis seems to support both hypotheses, as besides CCL2, CCL3 and CCR5 up-regulation, we also observed increased expression of MMP-9 in cancer cells grown under co-culture conditions with macrophages." (PMID 22353646, 2012). "For the purposes of the microarray data validation, we have selected 9 genes that may play the most important role in cancer cells-macrophages interactions: CCL2, CCL3, CD163, CSF1R, HIF1, Il-18, MMP9, VEGF-C, and Wnt7b." (PMID 22353646, 2012). "As a seven-transmembrane G protein-coupled receptor, CCR5 can bind to a variety of ligands CCL3 (MIP1α), CCL3L1, CCL4 (MP-1β), CCL5 (RANTES), CCL8 (MCP2), CCL11 (Eotaxin), CCL13 (MCP-4), and CCL16, which are reported to be highly expressed in most malignant tumors." (PMID 36167571, 2022). "Within the cancer cohort validation gene set, expression data for CCL3, was not available." (PMID 34830895, 2021). "Similarly, because of a significant pro-cancer effect, it is postulated that treatment may target the functioning of CCL3/MIP-1α, CCL5/RANTES." (PMID 32781743, 2020). "Therefore, MMP-2 may be the CCL3-responsive mediator, and may degrade the ECM leading to subsequent cancer migration and metastasis." (PMID 24047437, 2013). "However, carcinoma samples with MMP-11 positive MICs showed a more important increase in the mRNA level of 19 factors: IL-1, −5, −6, −8, −17 and −18, ADAM-8, −10, −15, and −23, ADAMTS-1, −2, and −15, IFNβ, MMP-1, as well as mediators related to inflammation (CCL-3, IRAK-4, MyD88 and NFκB)." (PMID 23145063, 2012). "In non-cancer cells such as dermal fibroblasts and primary hepatocytes chronic hypoxia does not change the expression of CCL3/MIP-1α and CCL4/MIP-1β." (PMID 32781743, 2020). "There are no reports on the recruitment of TAM by CCL3 or CCL4; they support the anticancer functions of monocytes, so they will not recruit TAM but will be more responsible for the infiltration of anti-cancer M1 macrophages." (PMID 33076281, 2020).